U8 (U8 small nucleolar RNA )
Synonyms: LOC124900517
Gene: Small nucleolar RNA gene on chromosome 2 (86,347,062 to 86,347,195, reverse strand). Ensembl gene ENSG00000202537.
Gene Ontology:
Biological process: RNA processing
Cellular component: nucleolus
Homologues: Orthologues: chimpanzee U8 (97% identical), macaque U8 (93% identical), guinea pig U8 (83% identical). Paralogues in human: U8 (87% identical), U8 (85% identical), U8 (84% identical), U8 (79% identical), U8 (78% identical), U8 (77% identical), U8 (76% identical), U8 (75% identical), U8 (74% identical), U8 (69% identical), U8 (68% identical), U8 (67% identical), and 2 more.